IL17A (interleukin 17A)
Diseases named in the same sentence as IL17A in open-access papers (continued):
Sharing a sentence is not in itself a finding about the gene and the disease.
rheumatoid arthritis (continued). "It has been described that, in the context of rheumatoid arthritis (RA), IL-17A leads to RANKL production by mesenchymal cells in the joint to activate the OCP for bone degradation." (PMID 32635380, 2020). "In this regard, there are several ongoing clinical trials using neutralizing antibodies against IL-17A for chronic human inflammatory diseases, such as chronic plaque psoriasis, psoriatic arthritis, ankylosing spondylitis, and rheumatoid arthritis." (PMID 31963845, 2020). "IL-17A or IL-17 is involved in several chronic diseases, including rheumatoid arthritis (RA), and it upregulates other proinflammatory cytokines, including IL-1β and IL-6." (PMID 31614911, 2019). "Cytokines IL-1β and IL-17A are detected in synovial fluid (SF) of rheumatoid arthritis (RA) and OA patients." (PMID 31002692, 2019). "During rheumatoid arthritis (RA), IL-17A is spontaneously produced by the synovium and this increased IL-17A level correlates with disease activity." (PMID 31396230, 2019). "TNFα, IL-17A, and IL-12/23 p40 levels in serum and synovial fluid from patients with ankylosing spondylitis (AS), rheumatoid arthritis (RA), osteoarthritis (OA), or healthy controls (HC) were measured by ELISA." (PMID 29880011, 2018). "Induction of IL-17A occurs in the synovial fluids from rheumatoid arthritis (RA) patients and in the renal biopsies from systemic lupus erythematosus (SLE) patients." (PMID 30214937, 2018). "Similar observations apply for rheumatoid arthritis (RA) where IL-17A triggers changes in the synovium that lead to synovitis and maintain local inflammation." (PMID 30693283, 2018). "Interleukin-17A (IL-17A) is considered an important pro-inflammatory cytokine but its importance in joint diseases such as rheumatoid arthritis (RA) is unclear." (PMID 28871176, 2017). "The aim of this study was to examine the association between the polymorphisms in IL17A and IL17F genes and rheumatoid arthritis." (PMID 27169372, 2016). "Over the last decade IL-17A has become recognised as a key mediator in a range of immune-mediated conditions including inflammatory bowel disease, rheumatoid arthritis and multiple sclerosis." (PMID 26774505, 2016). "Our observation that mast cells express a considerable amount IL-17A adds important information to this finding, because a role for mast-cell derived IL-17 has only been proposed in the development of joint destruction in rheumatoid arthritis." (PMID 26069967, 2015). "High circulating IL-17A levels have been observed in patients with chronic inflammatory diseases such as rheumatoid arthritis, multiple sclerosis and inflammatory bowel disease, and IL-17A is considered a proinflammatory cytokine." (PMID 25615631, 2015). "IL-17A is found at elevated levels in synovial fluid of patients with rheumatoid arthritis and has been shown to be involved in early rheumatoid arthritis development." (PMID 24692552, 2014). "The levels of IL-17A, IL-17F, IL-17RA, and IL-17RC are also high in the sera and inflamed synovium of patients with rheumatoid arthritis." (PMID 23956759, 2013). "Neurodegeneration in multiple sclerosis, synovial inflammation in rheumatoid arthritis, inflammatory bowl disease, and type I diabetes have all been shown to be in part mediated by IL-17A and IFN-γ." (PMID 22969766, 2012). "Studies have shown that IL-17A is upregulated and involved in the pathogenesis of various autoimmune inflammatory diseases such as rheumatoid arthritis, systemic lupus erythematosus, and systemic sclerosis." (PMID 22748016, 2012). "Prior human studies had suggested that the involvement of IL-17A in the pathogenesis of rheumatoid arthritis was limited to its initial phase characterized by the development of an autoimmune response." (PMID 22028860, 2011). "IL-17A expression was examined by ELISA and immunohistology in the rheumatoid arthritis (RA) joints." (PMID 19627579, 2009).
rheumatoid arthritis (continued). "While previous studies have highlighted TP’s suppression of IL-17A via Th17 inhibition or NF-κB signaling in conditions such as liver fibrosis and rheumatoid arthritis, our work uncovers a previously unrecognized mechanism: TP’s regulation of the Wnt5a/β-catenin axis in keratinocytes." (PMID 40365308, 2025). "Targeting key components of these pathways, such as IL-17A and its receptors, has shown promise in preclinical models and clinical trials for rheumatoid arthritis and may also be beneficial for gout management." (PMID 39611154, 2024). "However, the expression and functional response to IL-17A appears to be similar in the synovitis of psoriatic arthritis and rheumatoid arthritis." (PMID 38672170, 2024). "Similarly, atorvastatin revealed a potential immunomodulatory effect against rheumatoid arthritis by reducing IL-17A, TNF, and IL-6 levels." (PMID 38105357, 2023). "Furthermore, MCs are the predominant cellular source of IL-17A in the synovium of rheumatoid arthritis patients." (PMID 36396641, 2022). "Furthermore, IL-17A, IL-17F, and their receptors are found in the inflamed synovium of patients with rheumatoid arthritis and psoriatic arthritis." (PMID 35861937, 2022). "Furthermore, the role of IL-17A is well documented in a number of inflammatory diseases such as psoriatic arthritis, ankylosing spondylitis, and rheumatoid arthritis." (PMID 34544860, 2021). "Also, CD4+CD28- T lymphocytes isolated from the synovial fluid of rheumatoid arthritis-affected patients were capable of producing higher levels of IL-17A as compared with isolated CD4+CD28+ T lymphocytes." (PMID 34341698, 2021). "Similarly, IL-17A from T helper cells utilizes the IL-17A/IL-17RA axis to mediate rheumatoid arthritis-induced lung fibrosis." (PMID 34207528, 2021). "For example, there are studies of SNPs in IL17A associated with rheumatoid arthritis and systemic lupus erythematosus, but there are not enough studies in COPD, despite the pathophysiological role of IL17 and Th17 cells." (PMID 31964947, 2020). "IL‐17A is the best characterized IL‐17 family member that displays pro‐inflammatory functions and is implicated in the immunopathology of inflammatory arthritis including psoriatic arthritis (PsA), axial spondylitis (AxSpA), and to a lesser extent, rheumatoid arthritis (RA)." (PMID 31850514, 2020). "Orally administered HY7801 regulates immune biomarkers, including TNF-α, IFN-γ, IL-17A, IL-10, and IL-12, and might be useful in the treatment of rheumatoid arthritis." (PMID 32384794, 2020). "The objective of the present study was to evaluate the effects of Enalapril, Losartan and Valsartan on the production of IL-2, IL-10, IL-6, TNF, IFN-γ, IL-17A, IL-17F and IL-22 cytokines in PBMCs of patients with rheumatoid arthritis and evaluate this modulation with disease activity." (PMID 30288187, 2018). "Furthermore, in rheumatoid arthritis (RA), the most prevalent chronic inflammatory disease, IL-17A acts locally on synoviocytes and osteoblasts contributing to synovitis and joint destruction." (PMID 30693283, 2018). "Top canonical pathways in diabetic gastroparesis included genes involved with macrophages, fibroblasts and endothelial cells in rheumatoid arthritis, osteoarthritis pathway and differential regulation of cytokine production in macrophages and T helper cells by IL-17A and IL-17F." (PMID 30086735, 2018). "Furthermore, JNJ-54271074 suppressed IL-17A production in human PBMC from rheumatoid arthritis patients." (PMID 27905482, 2016). "Thus, for instance, both hypoxia and interleukin-17A (IL-17A) promote the migration and invasion of fibroblast-like synoviocytes (SFs), which are critical for the pathogenesis of rheumatoid arthritis (RA)." (PMID 26501341, 2015). "In addition, it is quite clear that VDR ligands directly target also Th17 cell subtype, as shown by the reduction of Th17 cytokines, such as IL-17A, IL-17F, and IL-22 by memory T cells in patients with early rheumatoid arthritis (RA)." (PMID 24895631, 2014).
rheumatoid arthritis (continued). "In rheumatoid arthritis, IL-17A may intensify local inflammation by promoting angiogenesis and recruiting innate immune cells into the joints." (PMID 24376862, 2013). "Their ability to suppress IL-17A functional activity was assessed in peripheral blood mononuclear cells (PBMCs) from healthy donors and personalized fibroblast-like synoviocytes (FLSs) from patients with axial spondyloarthritis (axSpA) and rheumatoid arthritis (RA)." (PMID 41754778, 2026). "Therefore, it has been suggested that the anti-IL-17A antibody is effective against PsA, causing osteogenesis of the joint, but not rheumatoid arthritis caused by bone and cartilage destruction." (PMID 39919800, 2025). "Cytokine inhibitors such as anti-TNF-α, anti-IL-17A, and anti-IL-6 have been used in other inflammatory-driven diseases such as rheumatoid arthritis (RA)." (PMID 34208697, 2021). "Our group also demonstrated that increased EBV viral DNA loads in patients with rheumatoid arthritis (RA) correspond with higher levels of serum IL-17A." (PMID 34040613, 2021). "Cyanidin could be used for rheumatoid arthritis (RA) treatment as Interleukin 17A/IL-17 receptor A (IL-17/17RA) signaling targeted therapy and could alleviate clinical symptoms, synovial growth, immune cell infiltration, and bone erosion in adjuvant-induced arthritis (AA) rats." (PMID 34776985, 2021). "Similarly, IL-17A and IL-17F were detected in synovial tissue from rheumatoid arthritis patients." (PMID 31827374, 2019). "Overexpression of IL-17A in healthy mouse knee joints induced rheumatoid arthritis (RA)-like pathology with features including joint inflammation, focal bone erosion and cartilage damage." (PMID 28202039, 2017). "This was studied in rheumatoid arthritis (RA) synoviocytes stimulated with IL-17A and tumor necrosis factor alpha (TNF-α), which act synergistically to induce a massive inflammatory signal." (PMID 28620392, 2017). "In PBMC from treatment-naive patients with early rheumatoid arthritis (RA), reduced IL-17A and increased IL-4 levels have been observed in the presence of 1α,25(OH)2D3." (PMID 25071589, 2014). "Previous studies reported that IL-17A promoted VEGF production in corneal neovascularization, osteoarthritis, and rheumatoid arthritis." (PMID 38007487, 2023). "In vivo rat model of rheumatoid arthritis (RA), DEX suppresses NLRC5, therefore reducing cytokine levels of IL-1β, IL-6, IL-17A, and TNF-α." (PMID 35628263, 2022). "For example, IL-17A and IL-22 are believed to act in concert in autoimmune pathogenesis and IL-17 has been shown to act synergistically with TNF-α, in the induction of IL-6 in rheumatoid arthritis." (PMID 34203644, 2021). "In patients with rheumatoid arthritis, TNF‐α and IL‐17A have been shown to promote NET formation contributing to the pathogenesis of the disease." (PMID 32473089, 2020). "Expression of IL17A and CD21L genes was assessed by RT-PCR, qRT-PCR and dPCR in synovia from 54 patients with rheumatoid arthritis." (PMID 30114200, 2018). "Tofacitinib, with specificity for JAK1 and JAK3, reduces IL-23 triggered IL-17A secretion from T cells of rheumatoid arthritis (RA) and psoriatric arthritis (PSA) patients in vitro, and was the first JAK inhibitor to be licensed for treatment of RA in the United States15,16." (PMID 30353145, 2018). "IL-25, IL-6, and bioactive IL-17A were quantified in rheumatoid arthritis (RA) patient plasma." (PMID 28620392, 2017). "Among the proinflammatory cytokines, IL-17A, IL-21 and IL-23 are considered as those which play crucial roles in the induction of local inflammation and cartilage destruction diseases such as rheumatoid arthritis (RA)." (PMID 27820818, 2016). "IL-17A and TNF exert a synergistic effect in FLS in rheumatoid arthritis by increasing the secretion of many factors, including IL-6, IL-8 and granulocyte-colony stimulating factor (G-CSF)." (PMID 27165410, 2016).
rheumatoid arthritis (continued). "TNF-α and IL-17A act on fibroblast-like synoviocytes (FLS) and contribute to cytokine production, inflammation, and tissue destruction in rheumatoid arthritis (RA)." (PMID 25904914, 2015). "Previous studies found that IL-17A could regulate MMPs, IL-1 and TNF in periodontitis, and found that IL-17 receptor deficiency results in impaired expression of IL-1 and MMP3/MMP9/MMP13 in rheumatoid arthritis, indicating that IL-17A also plays an important role in the regulation of MMPs." (PMID 25250801, 2014). "The objective of this study was to establish any effect of smoking on the inflammatory tissue lesions of rheumatoid arthritis via the AHR and IL-17A." (PMID 23036591, 2012). "Therefore, IL-17A and IL-17F may both participate in the pathogenesis of rheumatoid arthritis." (PMID 22028860, 2011). "Notably, in T cells, IL-17A/F, TNF-α, and CXCL1/2 were upregulated in LKP-treated mice, with KEGG enrichment of IL-17 and TNF signaling pathways, consistent with findings in rheumatoid arthritis where IL-17-producing Th17 cells drive synovial inflammation." (PMID 41459160, 2025). "A previous in vitro study on patients with rheumatoid arthritis observed that TNF blockade does not suppress the production of IL-17A and IL-22." (PMID 39409006, 2024). "IL-17A can also significantly up-regulate the expression level of MMP13 in FLSs, thereby inhibiting the expression of COL2A1 in chondrocyte in the co-culture system, promoting collagen degradation and mediating rheumatoid arthritis related cartilage damage." (PMID 35371044, 2022). "Additionally, it was shown in synovium of rheumatoid arthritis patients that TNF-α stimulates attraction of DCs and IL-17A secreting T cells." (PMID 35203534, 2022). "IL-17A neutralization is effective in psoriasis, rheumatoid arthritis, ankylosing spondylitis, but not Crohn’s disease where it increases inflammation and susceptibility to fungal infections." (PMID 34211477, 2021). "Additionally, B. longum RAPO significantly inhibited Th17 cells and Th17-related genes—IL-17A, IRF4, RORC, IL-21, and IL-23R—in the PBMCs of rheumatoid arthritis patients." (PMID 34867956, 2021). "IL-17D RNA has been detected in rheumatoid nodules, where IL-17A is absent, but not in peripheral blood mononuclear cells or in synovial fluid from patients with rheumatoid arthritis." (PMID 33244315, 2020). "In rheumatoid arthritis, the CD4+CXCR3+CCR6+ subset is known to express high levels of IFNγ with poor secretion of IL-17A,36 though we did not observe any associated cytokine profile in our remission patients." (PMID 31540934, 2019). "Others have shown that IL17A or IL17F gene polymorphisms play a role in Rheumatoid Arthritis (RA) and asthma, but there are fewer reports on associations of the IL17A gene polymorphisms with UC; particularly, there are no reports about IL17A gene polymorphism in Chinese UC patients." (PMID 22984500, 2012). "Studies have revealed that cytokines such as RORγt, IL-17A, and IL-21 expressed in the mucosa not only contribute to inflammatory bowel disease but also lead to elevated mRNA levels of IL-17A, IL-22, and TNF-α in knee joint tissues, which was observed in mouse models of rheumatoid arthritis." (PMID 41400824, 2026). "Moreover, EBV-positive Sjögren’s Syndrome patients had higher IL-21-producing T cells compared to controls, and elevated blood EBV DNA levels correlated with increased levels of IL-17A in rheumatoid arthritis patients but not in controls." (PMID 40722611, 2025). "IL-17A is critically involved in the pathogenesis of collagen-induced arthritis (CIA) in mice and rheumatoid arthritis (RA) in patients." (PMID 34122457, 2021). "Since IL-17 has been found to play an important role in the pathogenesis of spondyloarthropathy, it has been shown that IL-17a monoclonal antibody is effective in the treatment of ankylosing spondylitis, psoriatic arthritis and rheumatoid arthritis without serious adverse events." (PMID 32039436, 2020).
rheumatoid arthritis (continued). "IL-17A is a bone-destroying cytokine in numerous immune-mediated bone diseases including postmenopausal osteoporosis (PMOP), rheumatoid arthritis (RA), psoriatic arthritis (PsA) and axial spondylarthritis (axSpA)." (PMID 33613566, 2020). "Treatment of rheumatoid arthritis (RA), systemic lupus erythematosus (SLE), multiple sclerosis (MS), or Sjögren's syndrome (SS) patients with rituximab, a CD20 antibody that depletes B cells, also decreased the number of circulating Th17 cells and serum IL-17A levels." (PMID 23505568, 2013). "Interestingly, IκBζ was also found to be involved in regulating IL17A and TNF‐induced transcription factor, ELF3 in synovial fibroblasts collected from rheumatoid arthritis (RA) and OA patients." (PMID 36245291, 2022). "Furthermore, the highest enriched pathways of the miRNAs were IL‐17A signaling in airway cells, PEDF signaling, Wnt/β‐catenin signaling, and JAK family kinases in IL‐6‐type cytokine signaling, and role of macrophages, fibroblasts and endothelial cells in rheumatoid arthritis." (PMID 32500672, 2020). "The IL-17A plays a crucial role in induction of autoimmune diseases such as inflammatory bowel disease (IBD), experimental autoimmune encephalomyelitis (EAE), and rheumatoid arthritis (RA), as well as chronic inflammatory diseases." (PMID 26495322, 2015). "Th17/Th22 (CXCR3−CCR4+), Th17.1 (CXCR3+CCR4−), DP (CXCR3+CCR4+), and DN (CXCR3−CCR4−) CCR6+ memTh, cells sorted from PBMC of healthy donors or treatment-naïve early rheumatoid arthritis (RA) patients, were cocultured with SF from RA patients with or without anti-IL17A, anti-IFNγ, or 1,25(OH)2D3." (PMID 34082814, 2021).